BMI1 (BMI1 proto-oncogene, polycomb ring finger)
Diseases named in the same sentence as BMI1 in open-access papers (continued):
Sharing a sentence is not in itself a finding about the gene and the disease.
gastric cancer (continued). "In order to further verify the relationship between Bmi-1 and stem cell-like characteristics, we used immunohistochemical method to detect the expression of Bmi-1 in 101 primary site specimens of gastric cancer and 72 ovarian metastases specimens originated from gastric cancer." (PMID 27644439, 2016). "To test this hypothesis, we used microRNA (miRNA) expression profile chip to detect the changes of miRNA in gastric cancer cells after Bmi-1 knockdown." (PMID 27644439, 2016). "There was a positive correlation between Bmi-1 and miR-21 expression in gastric cancer tissues." (PMID 27644439, 2016). "The miRNA mediated Bmi-1 expression and functional significance in gastric cancer remained elusive." (PMID 26894855, 2016). "The expression of Bmi-1 is significantly correlated with gastric cancer patient survival." (PMID 26894855, 2016). "In summary, we discovered that the expression of Bmi-1 is regulated by miR-15a in gastric cancer." (PMID 26894855, 2016). "We have found that Bmi-1 and CBX7 were overexpressed in gastric cancer tissues and correlated with cancer progress and prognosis, while Mel-18 expression inversely correlated with Bmi-1 expression and Mel-18 could negatively regulate Bmi-1." (PMID 23874550, 2013). "In conclusion, we identified that TAMs could promote gastrointestinal cancer, especially gastric cancer, progression by downregulating miR-30e* and upregulating Bmi1." (PMID 24312366, 2013). "Bmi1 expression was inversely correlated with miR-30e* expression in gastric cancer." (PMID 24312366, 2013). "miRNA microarray analysis of a gastric cancer cell line co-cultured with macrophages was conducted, and using in silico methods to analyze the results, we identified miR-30e* as a potential regulator of Bmi1 expression." (PMID 24312366, 2013). "Taking it all together, BMI1 may become a new biomarker in supporting the diagnosis and determining the prognosis of gastric cancer in clinical practice though more studies still should be done." (PMID 22539939, 2012). "Overexpression of Bmi-1 in gastric cancer has been previously reported." (PMID 21059209, 2010). "The BMI1 oncogene is overexpressed in several human malignancies including gastric cancer." (PMID 20170541, 2010). "Collectively, our data suggest that Mel-18 and BMI1 not only play important roles in tumorigenesis, but may also involve in the progression and metastasis of gastric cancer." (PMID 20170541, 2010). "Based on these data, we hypothesized that gastric cancer cell lines and gastric tumors may also express high BMI1 and low Mel-18." (PMID 20170541, 2010). "Both Bmi-1 and Mel-18 are involved in the development and progression of gastric cancer." (PMID 21059209, 2010). "Importantly, we show that expression of Mel-18 is decreased in gastric cancer and is negatively correlated with the expression of BMI1 in both gastric cancer cells and normal gastric epithelial cells." (PMID 20170541, 2010). "To probe this hypothesis, first we analyzed the expression of BMI1 and Mel-18 in several gastric cancer cell lines." (PMID 20170541, 2010). "Based on these data, we hypothesized that gastric cancer may also express high Bmi-1 and low Mel-18." (PMID 21059209, 2010). "Our results showed that compared to GES-1, a normal immortal human gastric mucosal epithelial cell line, the majority of gastric cancer cell lines expressed high BMI1 (5 out of 8 at the RNA and protein levels) and low Mel-18 (4 out of 8 at the RNA level and 5 out of 8 at the protein level)." (PMID 20170541, 2010). "BMI1 was found to be overexpressed in gastric cancer cell lines and gastric tumors." (PMID 20170541, 2010). "Downregulation of BMI1 by Mel-18 overexpression or knockdown of BMI1 expression in gastric cancer cell lines led to upregulation of p16 (p16INK4a or CDKN2A) in p16 positive cell lines and reduction of phospho-AKT in both p16-positive and p16-negative cell lines." (PMID 20170541, 2010).
gastric cancer (continued). "Interestingly, we observed a reverse correlation between the expression levels of Bmi-1 and Mel-18 in gastric cancer." (PMID 21059209, 2010). "Our present data using gastric cancer cells also suggest that BMI1 and Mel-18 can regulate tumorigenesis, cell migration and metastasis at least partially independent of p16, which is a known tumor suppressor involved in regulation of cell proliferation and possibly metastasis." (PMID 20170541, 2010). "B-cell specific Moloney murine leukemia virus integration site 1 (Bmi-1) has been seen to have a negative relationship with RKIP expression and is associated with tumor size and prognosis of gastric cancers, but Bmi-1 does not directly influence RKIP expression." (PMID 36230521, 2022). "We previously reported an inverse relationship between B cell-specific Moloney murine leukemia virus integration site 1 (Bmi-1) and Raf kinase inhibitory protein (RKIP), which is associated with the prognosis of gastric cancer (GC)." (PMID 32580736, 2020). "Moreover, the miR-27a inhibitor and miR-155 inhibitor could also weaken the effects of Bmi-1 overexpression on migration, invasion and chemoresistance in gastric cancer cells." (PMID 32580736, 2020). "Moreover, ANRIL silence, miR-99a up-regulation, and BMI1 silence might be potential therapeutic strategies for gastric cancer." (PMID 30156609, 2018). "Our analysis of TCGA database indicated that BMI1 overexpression may predict gastric cancer patient survival, and TAT-BMI1 proteins reversed the USP22 knockdown-mediated decreased in cancer stem cell properties, and elevated the expression of stemness-associated genes." (PMID 28415621, 2017). "To determine whether miR-128 promotes gastric cancer migration, invasion, and proliferation by targeting Bmi-1, we forced the expression of miR-128 in AGS cell lines together with a construct containing the Bmi-1 coding sequence but lacking the 3′UTR of Bmi-1 mRNA." (PMID 28424413, 2017). "Since LMP1 induces promoter hypermethylation via activation of DNA methyltransferase 1 and the polycomb group protein Bmi-1, LMP1 may contribute to global methylation and epigenetic silencing of multiple cancer genes during the initial stages of EBV-associated gastric cancer." (PMID 28454117, 2017). "Thus, we speculated that miR-128 regulates gastric cancer tumorigenesis by directly targeting Bmi-1." (PMID 28424413, 2017). "However, despite the functional significance of Bmi-1 in regulating proliferation and progression, the clinical impact of Bmi-1 in gastric cancer is quite complex as patients with high levels of Bmi-1 had better survival than patients with low Bmi-1 expression." (PMID 26894855, 2016). "This study was to investigate whether and how Bmi-1 regulates stemness of gastric cancer." (PMID 27644439, 2016). "To determine whether miR-34a plays a role via Bmi-1, we used the co-transfection method to simultaneously change the expression of Bmi-1 and miR-34a in an exogenous way and observe the effect on characteristics of gastric cancer stem cells." (PMID 27644439, 2016). "In order to detect whether miR-21 plays a role in the downstream of Bmi-1, we utilized co-transfection to simultaneously change the expression of Bmi-1 and miR-21 in cells in an exogenous way and observed the effects on stem cell-like properties of gastric cancer cells." (PMID 27644439, 2016). "However, only Bmi-1 was confirmed as a target of miR-183 in the gastric cancer cells." (PMID 25295122, 2014). "Thus, our data suggest that overexpression of BMI1 in gastric tumors and cell lines may due to downregulation of Mel-18 in gastric cancer cells." (PMID 20170541, 2010). "Bmi-1 and Mel-18 might be novel molecular markers for gastric cancer." (PMID 21059209, 2010). "Our data suggest that Mel-18 and Bmi-1 may play crucial but opposite roles in gastric cancer." (PMID 21059209, 2010).
gastric cancer (continued). "Finally our studies suggest that determination of the expression of BMI1 and Mel-18 may help in supporting the diagnosis and determining the prognosis of gastric cancer in clinical practice." (PMID 20170541, 2010). "However, the exact role of BMI1 in gastric cancer is far from clear." (PMID 20170541, 2010). "Hence, detection of Mel-18 and BMI1 expression may be helpful in supporting the diagnosis and determining the prognosis of gastric cancer in clinical practice." (PMID 20170541, 2010). "BMI1, the core of PRC1, which ubiquitinates lysine 119 at histone H2A (H2AK119ub1), is highly expressed in gastric cancer (GC), colon cancer (CRC), and breast cancer." (PMID 37220590, 2023). "A positive correlation was observed between E2F1 and BMI1 (r = 0.422, p < 0.05), CD44 (r = 0.634, p < 0.05), OCT4 (r = 0.456, p < 0.05), and Nanog (r = 0.337, p < 0.05) in gastric cancer tissues." (PMID 33986804, 2021). "Very fascinatingly, we found that upregulation of HOXA11 in gastric cancer cells resulted in increased expression of cancer stem cell factors such as CD44, CD90, CD133 and Bmi1 as well as pluripotency markers Nanog and Sox2 and vice versa." (PMID 31695791, 2019). "Together, we provided a novel regulatory mechanism for ANRIL in gastric cancer, in which ANRIL silence down-regulated BMI1 via miR-99a, along with activation of the apoptotic pathway and inhibition of the Notch and mTOR pathways." (PMID 30156609, 2018). "In our study, we found that Bmi-1 can drive the EMT process by activating the PI3K/ AKT pathway in gastric cancer, and miR-128 can drive EMT by curbing the expression of Bmi-1." (PMID 28424413, 2017). "We found that gastric cancer cell migration, invasion, and proliferation were completely restored in the AGS cell line with forced miR-128 expression and Bmi-1 restoration." (PMID 28424413, 2017). "Immunofluorescence staining of gastric cancer tissues also showed strong nuclear co-localization of USP22 and BMI1." (PMID 28415621, 2017). "In gastric cancer, the signal of p-AMPK was lower in tumor (p < 0.001) and Bmi-1 expression higher in tumor (p < 0.001) than that of adjacent normal tissues." (PMID 26717043, 2016). "We found that expression of Bmi-1 and p-AMPK inversely changed in gastric cancer tissues; p-AMPK level was reduced, whereas Bmi-1 expression was increased, as compared to adjacent tissues." (PMID 26717043, 2016). "To clarify the role of Bmi-1 in stemness of gastric cancer, we checked the expression of Bmi-1 in microsphere and found that sphere cells from SGC7901 and MKN45 cell lines overexpressed Bmi-1 and other stem cell markers Oct-4, Sox2, Nanog, CD44, and CD133." (PMID 27644439, 2016). "Therefore, the results of Bmi-1 expression in gastric CSCs are still conflicting, and further research is required to clarify whether Bmi-1 plays a role in regulation of stemness in gastric cancer." (PMID 27644439, 2016). "In another gastric cancer cell line AGS, we decreased Bmi-1 expression by gene interference or overexpressed Bmi-1 and obtained similar results by the same methods (data not shown)." (PMID 27644439, 2016). "Results showed a positive relationship with Bmi1 and CD68/CD163 expression in gastric cancer and in colon cancer." (PMID 24312366, 2013). "Bmi-1 was also found to be a negative prognostic factor in gastric cancer and endometrial adenocarcinoma, each demonstrating heightened Bmi-1 expression to be indicative of worse clinical stage, lymph node metastases, and overall survival." (PMID 36726797, 2023). "More recently, we identified a significant correlation between GLUT1 and Moloney murine leukemia virus integration site 1 (Bmi-1) in gastric cancer (unpublished data, this study has been submitted but has not been published yet)." (PMID 35415241, 2022). "In gastric cancer, USP22 maintains CSC stemness by stabilizing BMI1 protein." (PMID 35935969, 2022).
gastric cancer (continued). "Importantly, we provided a novel regulatory mechanism of ANRIL in gastric cancer, by which ANRIL functioned through miR-99a-mediated modulation of BMI1, involved in the apoptotic pathway, and in Notch and mTOR signal pathways." (PMID 30156609, 2018). "Alterations of p16 after abnormal expression of BMI1, which is regulated by ANRIL via modulating miR-99a, indicated that ANRIL might be a prognostic marker for gastric cancer." (PMID 30156609, 2018). "Finally, miR-128 can inhibit epithelial-to-mesenchymal transition by targeting Bmi-1 and activating the PI3K/AKT pathway in gastric cancer cells." (PMID 28424413, 2017). "Many studies have shown that Bmi-1 can regulate EMT in various cancers, but it is unclear whether Bmi-1 can drive the EMT process in gastric cancer." (PMID 28424413, 2017). "Next, we made stable cells by ectopic expression of LKB1 in SGC-7901 cells, gastric cancer cell line in which endogenous LKB1 was very low and by infection of LKB1 shRNA in AGS, another gastric cancer cell line, and then measured mRNA and protein of Bmi-1." (PMID 26717043, 2016). "Bmi-1 positively regulates stem cell-like properties via upregulating miR-21, and miR-34a negatively regulates stem cell-like characteristics by negative feedback regulation of Bmi-1 in gastric cancer." (PMID 27644439, 2016). "miR-30e* expression was decreased in tumor regions compared with non-tumor regions in gastrointestinal cancer, and miR-30e* expression was inversely correlated with Bmi1 expression in gastric cancer, but not in colon cancer." (PMID 24312366, 2013). "Patients with high BMI1 expression survived significantly shorter than those with low or no BMI1 expression suggesting that BMI1 is a key regulator and a valuable molecular marker of therapy failure in gastric cancer patients." (PMID 20170541, 2010). "We also found that overexpression of Mel-18, as well as knockdown of BMI1 expression induces senescence and reduces malignancy in AGS cells, another gastric cancer cell line which expresses p16, and in NCI-N87 cells which do not express detectable p16 (data not shown)." (PMID 20170541, 2010). "Thus the overexpression of BMI1 correlated with high AKT activity and low p16 in gastric cancer cell lines." (PMID 20170541, 2010). "Besides, accumulated evidence shows that CBX7 has a similar function to BMI-1 in gastric cancer, suggesting that CBX7 may participate and function in a way related to BMI-1 regulation." (PMID 34659360, 2021). "Because PcG protein BMI1 may regulate AKT and ERK pathways, we analyzed the expression of total AKT, phospho-AKT(p-AKT), total ERK and phospho-ERK (p-ERK) in control, CBX7-overexpressing (CBX7-oe), and CBX7-shRNA (CBX7i) gastric cancer cell lines." (PMID 29422082, 2018). "The inhibitory efficiency for HGC-27 cells with higher Bmi-1 expression was higher than that for SGC-7901 cells with lower Bmi-1 expression, suggesting that Ad-Bmi-1i might have a specific inhibitory effect for gastric cancer in vivo." (PMID 27009837, 2016). "Here, we show that Bmi-1 positively regulates stem cell-like properties via upregulating miR-21, and miR-34a negatively regulates stem cell-like characteristics by negative feedback regulation of Bmi-1 in gastric cancer." (PMID 27644439, 2016). "In addition, Bmi-1 protein expression was upregulated in the gastric cancer cell lines and tissues (data not shown)." (PMID 25295122, 2014). "qRT-PCR analysis of resected cancer specimens showed that miR-30e* expression was downregulated in tumor regions compared with non-tumor regions, and Bmi1 expression was inversely correlated with miR-30e* expression in gastric cancer tissues, but not in colon cancer tissues." (PMID 24312366, 2013). "To determine whether BMI1 and Mel-18 regulate p16 and AKT during gastric carcinogenesis, we analyzed the expression of p16 and phosphorylated AKT in gastric cancer cell lines and gastric cancer tissues." (PMID 20170541, 2010).
gastric cancer (continued). "Accordingly, our present study suggests that regulation of gastric tumorigenesis and metastasis by Mel-18 and BMI1 may involve AKT, which was overexpressed in gastric cancer tissues and positively correlated with the depth of invasion and lymph node metastasis in gastric cancer patients." (PMID 20170541, 2010). "Importantly, here we show that Mel-18 is downregulated in gastric cancer cells and gastric tumors, and that there is a negative correlation between Mel-18 and BMI1 expression in gastric cancer cells." (PMID 20170541, 2010). "Our previous research revealed that Bmi-1 was overexpressed in gastric cancer (GC) and it's overexpression was an independent negative prognostic factor, suggesting it can be a therapeutic target." (PMID 27009837, 2016). "Furthermore, expression of CBX7 positively correlates with the expression of pAKT in gastric carcinoma but not with the expression of pERK, suggesting that AKT may be an important downstream effector of CBX7 similar to BMI1." (PMID 29422082, 2018).